CDH1 (cadherin 1)
Diseases named in the same sentence as CDH1 in open-access papers (continued):
Sharing a sentence is not in itself a finding about the gene and the disease.
lobular breast cancer (continued). "A subsequent study showed that CDH1 germline variants are enriched in patients with colorectal SRCC, in addition to lobular breast cancer patients." (PMID 36765680, 2023). "In our eleven families, half of the lobular breast cancers (8/15) in CDH1 carriers occurred after 50 years (mean age 54 years old (SD 19)." (PMID 37761816, 2023). "Hereditary diffuse gastric cancer (HDGC) is caused by germline pathogenic variants in the CDH1 and CTNNA1 genes and is characterized by a high prevalence of diffuse gastric cancer and lobular breast cancer." (PMID 37686589, 2023). "Six CDH1 carriers had diffuse gastric cancer (five families) and 11 women had lobular breast cancer." (PMID 37761816, 2023). "CDH1 germline variants have been linked to heritability in diffuse gastric (DGC) and lobular breast cancer (LBC)." (PMID 34949788, 2022). "Genetic testing for CDH1 variants should be considered in families with CLP and history of either diffuse-type gastric or lobular breast cancer." (PMID 36246616, 2022). "Inactivating mutations in the CDH1 gene, encoding the cell adhesion protein E-cadherin, cause hereditary diffuse gastric cancer syndrome (HDGC), as well as being a hallmark of sporadic diffuse gastric cancers and lobular breast cancers." (PMID 35406381, 2022). "Based on this report, it appears quite reasonable to expand the criteria to include a recommendation for CDH1 genetic testing in individuals with lobular breast cancer at any age with a personal or family history of CLP." (PMID 36246616, 2022). "Subsequent reports noted that individuals with germline CDH1 pathogenic variants were predisposed to both DGC and lobular breast cancer (LBC)." (PMID 34949788, 2022). "Pathogenic germline CDH1 mutations lead to a lifetime risk of developing DGC and lobular breast cancer (LBC) of up to 70% and 40%, respectively." (PMID 35008338, 2021). "They restored full‐length E‐cadherin expression and function from a PTC interrupted CDH1 gene, which causes hereditary diffuse gastric cancer (HDGC) syndrome including lobular breast cancer (LBC), in mammalian cell lines using sup‐tRNAArg." (PMID 33567469, 2021). "Germline inactivating variants of CDH1 are causative of hereditary diffuse gastric cancer (HDGC), a cancer syndrome characterized by an increased risk of both diffuse gastric cancer and lobular breast cancer." (PMID 35008266, 2021). "In the last decade, we and others have provided evidence that the disease spectrum of CDH1 mutation carriers includes DGC, lobular breast cancer, cleft lip/palate, and the blepharocheilodontic syndrome." (PMID 34503169, 2021). "The first description of CDH1 germline mutations was reported in Maori kindred and families with diffuse gastric cancer (DGC) and lobular breast cancer (LBC) aggregation." (PMID 33809393, 2021). "HDGC is an autosomal dominant cancer syndrome linked to CDH1 (E-cadherin) inactivating germline mutations and characterized by high prevalence of diffuse gastric cancer (DGC) and lobular breast cancer (LBC)." (PMID 34503169, 2021). "Individuals with a higher risk of lobular cancer including those with CDH1 pathogenic variants, LCIS or lobular breast cancer family history should be considered for MRI breast screening." (PMID 34312777, 2021). "Hereditary diffuse gastric cancer (HDGC) caused by CDH1 variants predisposes to early-onset diffuse gastric (DGC) and lobular breast cancer (LBC)." (PMID 34503274, 2021). "Genetic linkage analysis and subsequent DNA sequencing has identified germline CDH1 mutations as a primary cause of HDGC (70%–80% lifetime risk with a positive family history) and lobular breast cancer in women (40% lifetime risk)." (PMID 32260281, 2020). "Germline mutations in E‐cadherin gene (MIM 192,090; CDH1) are associated with autosomal‐dominantly inherited cancer syndrome characterized by hereditary diffuse gastric cancer (HDGC), lobular breast cancer (BC), and in some families, cleft lip/palate." (PMID 32886433, 2020).
lobular breast cancer (continued). "Germline mutation in the E-cadherin gene (CDH1) is associated with familial cases of diffuse type gastric cancer and lobular breast cancer." (PMID 31892987, 2020). "Families affected by CDH1 germline mutations show a strong aggregation for diffuse gastric cancer (DGC) and lobular breast cancer (LBC)." (PMID 32560361, 2020). "Germline mutations in E‐cadherin (CDH1) gene are associated with autosomal‐dominantly inherited cancer syndrome characterized by diffuse gastric cancer, lobular breast cancer, and in some families, cleft lip/palate." (PMID 32886433, 2020). "Pathogenic variants in CDH1, encoding epithelial cadherin (E-cadherin), have been implicated in hereditary diffuse gastric cancer (HDGC), lobular breast cancer, and both syndromic and non-syndromic cleft lip/palate (CL/P)." (PMID 32260281, 2020). "The E-cadherin gene (CDH1) is frequently mutated in diffuse gastric cancer and lobular breast cancer, and germline mutations predispose to the cancer syndrome Hereditary Diffuse Gastric Cancer." (PMID 30066183, 2019). "Somatic mutations in CDH1 are common in diffuse gastric cancer (DGC) and lobular breast cancer (LBC)." (PMID 31467357, 2019). "Somatic mutations in CDH1 occur frequently in diffuse gastric cancer (DGC) and lobular breast cancer (LBC) and its downregulation is a hallmark of the epithelial–mesenchymal transition." (PMID 30066183, 2019). "Germline CDH1 mutations, classically associated with hereditary diffuse gastric cancer (HDGC), also imply an increased lifetime risk of developing lobular breast cancer (LBC) in a highly penetrant autosomal dominant manner." (PMID 31028995, 2019). "The dominant influence of mutations in CDH1 and PIK3CA reflects the recent results from TCGA showing that these two genes harbor by far the most frequently recurring mutations in lobular breast cancer." (PMID 27334989, 2016). "Direct functional effect of CDH1 germ-line nonsense and missense mutations increases risk of Hereditary Diffuse Gastric Cancer (HDGC), and in some instances to lobular breast cancer." (PMID 27566565, 2016). "Despite E-cadherin being the obvious candidate for such a predisposition, early work suggested CDH1 germline variants are rare in familial lobular breast cancer but do account for some cases of bilateral ILC." (PMID 25849106, 2015). "Studies suggest that the reduction in estrogen levels during menopause may lead to alterations in CDH1 expression, potentially contributing to the development of lobular breast cancer." (PMID 40757085, 2025). "This group has been newly defined with relevant CDH1 mutations in individual families, who present only with lobular breast cancers, but not with diffuse gastric cancers." (PMID 35448173, 2022). "All ALH/LCIS (n = 14) and non-neoplastic epithelium samples (n = 8) in this study showed methylation signals employing non-quantitative MSP, leading the authors to the conclusion that CDH1 gene methylation is an early event in lobular breast cancer development." (PMID 36139537, 2022). "Unfortunately, there is no central database tracking the outcomes of CDH1-mutation patients, and therefore counseling patients on secondary cancer risks beyond lobular breast cancer is difficult." (PMID 34073553, 2021). "Pathogenic mutations of CDH1 are also the leading cause of hereditary diffuse gastric cancer (HDGC), whose first clinical manifestation could be lobular breast cancer." (PMID 34926254, 2021). "Another gene, CDH1, which is considered a cancer driver for hereditary lobular breast cancer, presented a non-pathogenic variant in this cohort of TNBC samples." (PMID 34944094, 2021). "Inactivating germline mutations in the CDH1 gene (encoding the E-cadherin protein) are the genetic hallmark of hereditary diffuse gastric cancer (HDGC), and somatic CDH1 mutations are an early event in the development of sporadic diffuse gastric cancer (DGC) and lobular breast cancer (LBC)." (PMID 35008338, 2021).
lobular breast cancer (continued). "In addition to their role in HDGC, CDH1 mutations are commonly reported in sporadic DGC and lobular breast cancer, and miRNA-mediated suppression of CDH1 has been reported in intestinal-type gastric cancer." (PMID 35008266, 2021). "In sporadic diffuse gastric cancer, alterations in the gene encoding E-cadherin (CDH1) are found preferentially in exons 7 to 9, while in lobular breast cancers they are spread along the gene, with no preferential hotspot." (PMID 22470475, 2012). "More than 25 years ago, CDH1 pathogenic variants (PVs) were identified as the primary cause of hereditary diffuse gastric cancer (HDGC), an inherited cancer syndrome that increases the lifetime risk of developing diffuse gastric cancer (DGC) and lobular breast cancer (LBC)." (PMID 39379994, 2024). "Some genetic-level CDH1 alterations include inactivating mutations and loss of heterozygosity (LOH), found in infiltrating lobular breast carcinomas, and heterozygous germline mutations that increase the lifetime risk of developing diffuse gastric cancer and lobular breast cancer." (PMID 38698370, 2024). "The CDH1 (E-cadherin, MIM *192090) gene is an ascertained and common cause of hereditary diffuse gastric cancer (OMIM #137215), an autosomal dominant condition with high penetrance (up to 76% at 80 years of age) for early-onset diffuse gastric cancer and lobular breast cancer." (PMID 37509701, 2023). "Recent evidence has emerged demonstrating that CDH1 mutations may result in lobular breast cancer and in several congenital abnormalities, without personal or family history of GC." (PMID 33809393, 2021). "On the other hand, carriers of mutations in the gene encoding E-cadherin (CDH1) have a significant risk (more than 70%) of developing hereditary diffuse gastric cancer, and women with CDH1 mutations are at high risk (cumulative risk of about 40%) of lobular breast cancer." (PMID 34722557, 2021). "Over the last decade, the role of E-cadherin in cancer etiology has been intensively investigated, identifying that pathogenic variants in CDH1 are present in multiple types of cancer, including hereditary diffuse gastric cancer (HDGC) and lobular breast cancer." (PMID 32260281, 2020). "Thus, HDGC is not characterized by the presence of gastric polyposis; it is determined by a complete inactivation of the CDH1 gene, resulting in reduced or even absent expression of E-cadherin, which leads to an increased risk of developing diffuse gastric cancer or lobular breast cancer." (PMID 40217971, 2025). "Lastly, the spectrum of CDH1-related cancers probably not only includes DGC and lobular breast cancer but also signet ring cell colorectal cancer." (PMID 37761816, 2023). "HLBC is classified as the presence of a CDH1 GPV in either an affected individual or a family with one or more lobular breast cancer cases, but without any diffuse gastric cancer." (PMID 37258796, 2023). "Guidelines for the management of CDH1 carriers state BRRM can be considered in hereditary lobular breast cancer and hereditary diffuse gastric cancer, however it is not generally recommended for those aged under 30 years or over 60 years." (PMID 37258796, 2023). "Therefore, we suggest that CDH1 genetic testing criteria also include testing for unaffected individuals with a family history of CLP and diffuse gastric cancer or lobular breast cancer." (PMID 36246616, 2022). "Mutation analysis identified the homophilic epithelial cell adhesion gene CDH1 encoding E-cadherin, located at 16q22.1, as a TSG, but only in the histological subset of lobular breast cancer and not in the more frequent ductal breast cancer." (PMID 16280054, 2005). "Pathologically, inactivation or absence of CDH1 expression can decrease intercellular junctions and thus promote cancer invasion and metastasis, as seen in diffuse gastric cancer and lobular breast cancer." (PMID 31598425, 2019).
lobular breast cancer (continued). "For carriers of CDH1 GPVs without a family history of DGC, or with a family history of lobular breast cancer only, PTG should still be considered." (PMID 37258796, 2023).
invasive lobular carcinoma (112 papers, 1997 to 2026). "Somatic CDH1 pathogenic variants are associated with invasive lobular carcinoma (ILC), which shows a tenfold higher enrichment than infiltrating ductal carcinoma, underscoring the need for CDH1 genetic testing in women with ILC." (PMID 40366456, 2025). "The pathogenic germline variants of CDH1 are linked to a lifetime risk of up to 55% for invasive lobular carcinoma, primarily due to the downstream loss of E‐cadherin‐mediated adhesion." (PMID 41049266, 2025). "CDH1 (E-cadherin) bi-allelic inactivation is the hallmark alteration of breast invasive lobular carcinoma (ILC), resulting in its discohesive phenotype." (PMID 38347189, 2024). "This subtype is mostly luminal type exhibiting common genetic alterations such as gains and losses of chromosome 16q/16p, which are located on the CDH-1 gene, also resulting in E-Cadherin protein loss in >80% of invasive lobular carcinomas." (PMID 38015260, 2024). "Of note, while CDH1 mutations are associated with invasive lobular carcinoma, those mutations are found in less than 1% of all BC patients." (PMID 38627285, 2024). "In our series, 2 patients with CDH1 mutations were classified as having invasive lobular carcinoma and 1 was classified as having invasive ductal carcinoma (n = 1)." (PMID 38229073, 2024). "Although some studies have identified abnormalities in adhesion factors other than E-cadherin, the molecular mechanisms underlying E-cadherin abnormalities in CDH1-unaltered invasive lobular carcinoma remain poorly understood." (PMID 39201647, 2024). "CDH1, a likely tumour suppressor gene, encodes cell adhesion molecule E-cadherin, with CDH1 mutations (and abnormal methylation patterns) associated with invasive lobular breast carcinoma." (PMID 38304083, 2024). "Invasive lobular carcinoma exhibits unique morphological features frequently associated with alterations in CDH1." (PMID 39201647, 2024). "This is followed by invasive lobular carcinoma, observed in 5–15% of patients, characterized by mutations in epithelial cadherin (CDH1) and a distinctive growth pattern." (PMID 39065193, 2024). "Inactivation of CDH1 is considered to be a genetic hallmark of invasive lobular breast carcinoma, with CDH1 mutations in 46–65% of cases." (PMID 38229073, 2024). "Women with germline pathogenic variants in CDH1, which encodes E-cadherin protein, are at increased lifetime risk of invasive lobular carcinoma (ILC)." (PMID 37758801, 2023). "Mutation of PIK3CA, NTRK3, CDKN1B, HER2/neu, and CDH1, the genes encoding E-cadherin 1, have been reported, and they are known to be pathogenic in invasive lobular carcinoma of the breast." (PMID 34064849, 2021). "In the present work, we found that CDH1 transcript levels were lower in invasive lobular carcinomas either in 16q-loss groups (A, B1, and D) and in the 16q-disomic CTRL-group when compared to corresponding ductal carcinomas or to normal breast tissue." (PMID 33808143, 2021). "E-cadherin is considered a tumor suppressor and loss of E-cadherin (CDH1) expression is a cardinal feature of invasive lobular carcinoma of the breast." (PMID 33525380, 2021). "The aggressive behavior of invasive lobular carcinoma combined with the high penetrance of CDH1 mutations justifies breast Risk-Reducing options." (PMID 31028995, 2019). "A deleterious mutation in CDH1 was identified in the invasive lobular carcinoma (ILC), BR15-016T, consistent with a previous study showing frequent CDH1 mutation in ILC." (PMID 29464067, 2018). "Mutation or deletion of the CDH1 gene has been reported in 30–60% cases of invasive lobular carcinoma (ILC)." (PMID 27811364, 2016). "Female mice carrying specific alleles of the Cdh1 gene, responsible for the production of E-cadherin, can be prompted to develop invasive lobular breast carcinoma (ILC) through the administration of lentiviral vectors expressing Cre recombinase, the CRISPR/Cas9 system, or a combination of both." (PMID 39338894, 2024).
invasive lobular carcinoma (continued). "Indeed, CDH1-inactivating mutations have been found in 15–56% of invasive lobular breast carcinomas, and the majority of such mutations are associated with 16q-loss, thus generating the typical biallelic inactivation of tumor suppressor genes." (PMID 33808143, 2021). "However, both histological subtypes have shown a frequent 16q-loss, independently by the presence of inactivating point mutations of CDH1, and the invasive lobular carcinomas have shown a reduced expression of CDH1 at both the mRNA and protein level." (PMID 33808143, 2021). "Contralateral mastectomy for CDH1 mutation carriers diagnosed with invasive lobular carcinoma may be considered on an individual basis." (PMID 30568591, 2018). "Because of the high lifetime risk of invasive lobular carcinoma, women with CDH1 mutations should undergo annual radiologic surveillance, with bilateral breast magnetic resonance imaging being the preferred modality, along with annual clinical breast examination." (PMID 30568591, 2018). "Nonetheless, we note that restoration of the full epithelial traits is not necessary for all types of metastases, as shown in most cases of invasive lobular carcinoma of the breast, in which E-cadherin expression is completely lost due to CDH1 mutation but macrometastases can still be formed." (PMID 30043221, 2018). "However, CDH1 mutations are connected to an aggressive BC pattern characterized by lymphovascular invasion and axillary lymph node metastases, particularly within Invasive Lobular Carcinoma (ILC), which accounts for 5–15% of BC cases and is linked to CDH1 loss of function mutations." (PMID 39390525, 2024). "This narrative review integrates a synthesis of peer-reviewed literature with bioinformatics analysis of publicly available datasets to explore the role of the CDH1 gene in the pathogenesis and progression of invasive lobular carcinoma (ILC) of the breast." (PMID 40757085, 2025). "Most invasive lobular breast carcinomas (ILBCs) are luminal‐type carcinomas with an HER2‐negative phenotype (ERBB2 or HER2 un‐amplified) and CDH1 mutations." (PMID 38335502, 2024). "The proposed role of CDH1 (E-cadherin gene) methylation as a mechanism of gene inactivation in invasive lobular carcinoma (ILC) remains inconclusive." (PMID 38713384, 2024). "For example, loss of epithelial cadherin (E-cadherin, encoded by CDH1) is considered as the most prominent cancer driving event in invasive lobular carcinoma of the breast (ILC), as well as hereditary and a subset of sporadic diffuse gastric cancer." (PMID 37255594, 2023). "In the first work, the authors were able to model invasive lobular breast carcinoma by sgRNA-assisted KO of PTEN, in female Cas9-knock-in and tissue-specific KO mice for the Cdh1 gene, encoding for E-cadherin." (PMID 37686639, 2023). "In other words, invasive lobular carcinomas had a CDH1 expression lower than ductal carcinomas both in the presence (groups A, B1, and D) and the absence of 16q-loss (CTRL group)." (PMID 33808143, 2021). "CDH1 germline mutations have been associated with hereditary lobular breast cancer and hereditary diffuse gastric cancer, while a recent study linked mutations in CDH1 and PIK3CA to the immune-related invasive lobular carcinoma of the breast." (PMID 32471470, 2020). "Recently, molecular analyses of invasive lobular carcinomas established that these tumors have a distinct genomic profile compared to IBC-NST, exhibiting a high frequency of CDH1 mutations, loss of PTEN, activation of AKT, and mutations in TBX3 and FOXA1." (PMID 32487046, 2020).